PPARG (peroxisome proliferator activated receptor gamma)
Diseases named in the same sentence as PPARG in open-access papers (continued):
Sharing a sentence is not in itself a finding about the gene and the disease.
breast cancer (continued). "Furthermore, PPARγ activation can exert antiproliferative effects in a variety of cancer types, including breast cancer." (PMID 30456386, 2018). "PPARγ was shown to protect ErbB2-positive breast cancer cells from palmitate-induced toxicity." (PMID 29599799, 2018). "This suggests a key role for PPARγ in luminal breast cancer." (PMID 30456386, 2018). "Moreover, deletion of Lats2 nearly abolished the death of cultured PyMT mouse tumor cells upon RGZ treatment, further confirming that sensitivity of lumB breast cancer cells to PPARγ activation is LATS2 dependent." (PMID 30456386, 2018). "However, there is other proof of the tumorigenic potential of PPARγ activation, such as in colorectal cancer, breast cancer, and urological cancer." (PMID 29966227, 2018). "Thus, it is uncertain if PPARγ agonists will have a beneficial effect as an anti-fibrotic therapy in breast cancer." (PMID 29487713, 2018). "One recent study has shown that the activation of PPARγ induces autophagy in breast cancer cells." (PMID 28460464, 2017). "There are several lines of evidence that VDR, RXR or PPARγ may be of relevance in breast cancer tumor-biology." (PMID 28427429, 2017). "We hypothesize that PPARγ in macrophages impedes breast cancer development by inhibiting inflammation." (PMID 27692066, 2016). "These intriguing observations suggest that PPARγ plays an anti-inflammatory role in macrophage and mammary gland, which may influence breast cancer." (PMID 27692066, 2016). "A recent study showed that thiazolidinedione-activated PPARγ had an ability to repress the proliferation of estrogen-dependent breast cancer cells and PPARγ might act as a therapeutic target in human breast cancer." (PMID 27323819, 2016). "Representative sections of normal mammary tissue and mammary tumours from PPARγ-WT and PPARγ-MG KO mice in each treatment group were hematoxylin and eosin (H&E) stained and examined in a blinded fashion by collaborating pathologists for changes in morphological characteristics." (PMID 25889730, 2015). "This may be reflective of the decreased mammary tumour progression in DMBA + ROSI-treated PPARγ-WT mice." (PMID 25889730, 2015). "In contrast, other 2 studies showing that PPARγ induced ER stress examined the effects of PPARγ agonists on cells derived from tumors such as RINm5F cell line derived from rat insulinoma and breast cancer cell line, MCF-7." (PMID 26061913, 2015). "Alternatively, the inherent cellular heterogeneity of these mammary tumours, that likely contain differing amounts of PPARγ expressing stromal adipocytes, endothelial cells and immune cells, may contribute to the observed variability." (PMID 25889730, 2015). "This marked increase in Cox-2 protein levels among DMBA + ROSI-treated PPARγ-MG KO tumours may partially explain the poor survival and mammary tumour outcomes within this study group." (PMID 25889730, 2015). "Together, these data emphasize the use of PPARγ ligands may be beneficial as novel chemotherapeutic agents for the treatment of a subpopulation of breast cancer patients, and that PPARγ expression may serve as a strong predictive biomarker of patient response." (PMID 25889730, 2015). "Interestingly, DMBA + ROSI-treated PPARγ-WT mice had reduced PTEN expression among mammary tumours than observed in mammary tumours from respective DMBA Only controls." (PMID 25889730, 2015). "15d-PGJ2 exerted its effects on breast cancer and bone cells via PPARγ-independent pathways." (PMID 25859665, 2015). "These interesting observations underscore the importance of personalized medicine, and the need for characterizing normal breast and mammary tumour epithelial expression of PPARγ before considering TZD-like drugs as chemotherapeutic strategies for breast cancer patients." (PMID 25889730, 2015). "Herein, morusin might act as an agonist of C/EBPβ and PPARγ, upregulate expressions of C/EBPβ and PPARγ, activated the cascade of adipogenic differentiation of breast cancer cells." (PMID 26538209, 2015).
breast cancer (continued). "The aim of this study was to determine whether PPARG participates in the 6IL antiproliferative and apoptotic effects on the mammary cancer cell line MCF-7." (PMID 26376791, 2015). "While a protective role of PPARγ expression was postulated in breast tumors and TZDs also acted preventive on the development of breast cancer in humans, the chemopreventive effect on colon cancer was not consistent with a protective role of PPARγ expression in tumor samples." (PMID 25866814, 2015). "DMBA Only-treated PPARγ-MG KO mammary tumours showed comparatively more benign characteristics." (PMID 25889730, 2015). "Similarly, DMBA + ROSI-treated PPARγ-MG KOs showed a significant decrease in mammary tumour latency compared to similarly treated PPARγ-WT mice (with 25% of mice developing palpable mammary tumours at week 16 vs. 21.5, respectively; p < 0.05)." (PMID 25889730, 2015). "Although a possible mosaic expression pattern of the MMTV promoter cannot be discounted, differing percentages of stromal PPARγ expressing cells may also explain the variability of PPARγ expression observed in PPARγ-MG KO mammary tumours." (PMID 25889730, 2015). "Apart from the fact that the role of the PPARG/RXRA heterodimer in urothelial cancer is exchanged with the ESR1 hormone receptor in breast cancer, the key transcription factors FOXA1 and GATA3 are downregulated in the basal/SCC-like subtypes of both tumor types." (PMID 26008846, 2015). "In order to investigate the role of the conserved acetylation sites of Pparγ in lipogenesis, ErbB2 overexpressing breast cancer cells were used and lysyl residues were substituted with alanine (K to A) or glutamine (K to Q) to generate residues that were incapable of being acetylated." (PMID 25229978, 2014). "We tested whether PTER-ITC mediates its anti-proliferative and pro-apoptotic effects in breast cancer cells through activation of the PPARγ signaling cascade." (PMID 25119466, 2014). "Ligand-induced PPARγ activation can induce apoptosis in breast, prostate and non-small cell lung cancer, and PPARγ ligand activation is reported to inhibit breast cancer cell invasion and metastasis." (PMID 25119466, 2014). "This coincides with our data, where using pharmaceutical inhibitors, we show that activation of p38 and JNK pathways, but not of ERK, is necessary and sufficient to phosphorylate PPARγ and cause subsequent apoptosis in the breast cancer cell lines studied." (PMID 25119466, 2014). "Generally speaking, cytoplasmic localization of PPARγ could become an important therapeutic target in breast cancer for several reasons." (PMID 23939428, 2013). "Taken together, these finding demonstrate that combined treatment of γ-tocotrienol with PPARγ antagonists display synergistic anticancer activity and may provide some benefit in the treatment of human breast cancer." (PMID 23431460, 2013). "Taken together these results suggest that inhibition of PPARγ expression and/or activity may be beneficial in the treatment of breast cancer." (PMID 23431460, 2013). "However, more studies are required to fully understand the roles of cytoplasmic PPARγ in human breast cancer." (PMID 23939428, 2013). "PPARγ is highly expressed in fatty tissues and many human cancers, including breast cancer." (PMID 23939428, 2013). "It is also clearly evident that use of γ-tocotrienol in combination with PPARγ antagonist may have potential therapeutic value in treatment of breast cancer in women." (PMID 23431460, 2013). "Because Skp2 is located downstream in the MAPK signaling pathway, we have in the present study tested the hypothesis that Skp2 overexpression can provoke cytoplasmic localization of PPARγ upon MEK1-dependent mechanisms in human breast cancer cells." (PMID 23939428, 2013). "However, the clinical pathological significance of cytoplasmic PPARγ is not completely understood in human breast cancer." (PMID 23939428, 2013). "Studies have shown that PPARγ is overexpressed in many types of breast cancer cells." (PMID 23431460, 2013).
breast cancer (continued). "In addition, Skp2 overexpression can provoke cytoplasmic localization of PPARγ upon MEK1-dependent mechanisms in human breast cancer cells by nuclear-cytosolic fractionation technology and immunofluorescence microscopy analysis." (PMID 23939428, 2013). "Combined treatment of γ-tocotrienol and PPARγ agonists caused an increase in transcription activity of PPARγ along with increased expression of PPARγ and RXR, and decrease in PPARγ coactivators, CBP p/300, CBP C-20, and SRC-1, in both breast cancer cell lines." (PMID 23431460, 2013). "The changes in the subcellular localization of PPARγ may represent a novel target for selective interference in patients with breast cancer." (PMID 23939428, 2013). "Furthermore, Western blot and immunofluorescence microscopy analysis were used to study the relationship between expression of cytoplasmic PPARγ and Skp2 expression in human breast cancer cells in vitro." (PMID 23939428, 2013). "In other words, cytoplasmic PPARγ may lose the ability to reduce cell proliferation and induction of apoptosis in breast cancer cells." (PMID 23939428, 2013). "The present study was designed to determine if pharmacological inhibition of PPARγ could sensitize mammary tumor growth to antiestrogen therapy." (PMID 22538444, 2012). "Enhancement of BRCA1 expression by PPARγ has been reported in MCF-7 breast cancer cells." (PMID 22701472, 2012). "Comparable to the finding in the N-methyl-N-nitrosourea (NMU)-induced breast cancer model in Sprague-Dawley rats, PPARγ was increased at both the protein and mRNA level in the mammary gland of ACI rats when treated with γ-TmT while ERα expression was decreased." (PMID 22254089, 2011). "PPARγ was expressed at highest levels in human breast cancer cell lines." (PMID 21080969, 2010). "PPARγ protein was expressed at highest levels in human breast cancer cell lines." (PMID 21080969, 2010). "Considering the abundance of PPARγ receptor and elevated NHE1 expression in a variety of cancer cells including breast cancer and their absolute dependence on MnSOD it is of interest to explore PPARγ agonists for selectively tailoring the expression of NHE1 and MnSOD." (PMID 19958503, 2009). "Also, MAZ drives tumor-specific expression of PPARG in breast cancer cells, a nuclear receptor that plays a pivotal role in breast cancer." (PMID 19737418, 2009). "PPARγ expression is also higher in ERBB2-positive breast cancer cells." (PMID 19298655, 2009). "PPARg has been found to be expressed in normal breast epithelium and breast cancers." (PMID 22276018, 2009). "This study shows that the adipogenic transcription factor PPARγ is critical for ERBB2-positive breast cancer cells to convert the high levels of fatty acids that they produce into triglycerides, allowing them to avert the cell death that results from lipotoxicity." (PMID 19298655, 2009). "In MCF-7 breast cancer cells PPARγ upregulated asimilar spectrum of CDKIs." (PMID 18528521, 2008). "PPARA, PPARD, and PPARG were involved in many of the indirect effects identified in breast cancer." (PMID 18358079, 2008). "The presence of PPARγ suppression by ERα in breast cancer cells might be a result of weak basal PPARγ transcriptional activity in these cells." (PMID 18584035, 2008). "PPARγ is expressed predominantly in white adiposetissue, intestine, endothelial cells, smooth muscle and macrophages, and is the major isotype expressed in the mammary gland, andin primary and metastatic breast cancer and breast cancer cell lines." (PMID 18566686, 2008). "Moreover, they described a reduction in the overall growthrate of breast cancer cells when treated witha PPARγ agonist." (PMID 19096712, 2008). "In vitro and in vivoresearch studies support a role for PPARγ agonists in breast cancer therapy." (PMID 19125177, 2008). "Indeed, initialstudies demonstrated alterations of cellular differentiation, indicative ofapoptosis in a breast cancer setting, after PPARγ agonist stimulation." (PMID 19096712, 2008).
breast cancer (continued). "PPARγ is expressed in normal breast tissueand in many primary breast carcinoma specimens." (PMID 18645617, 2008). "Since complete loss of PPARγ signaling in clinicalbreast tumors seems to be a rare event, it is likely that patientsundergoing chronic treatment with chemical ligands for PPARγ will experiencealteration in the behavior of both breast carcinoma cells and their normalcounterparts." (PMID 18645617, 2008). "The concept that cyclin D1 regulates PPARγ function has additional implications for breast cancer, wherein PPARγ is known to promote breast epithelial cell differentiation, and histological analyses of breast cancer specimens revealed that PPARγ is reduced in tumors with a high cyclin D1 index." (PMID 16863592, 2006). "A parallel might be drawn between the effect of fenofibrate (a PPARα agonist) in endometrial cancer and thiazolidenediones (TZDs, PPARγ agonists), such as rosiglatazone and troglitazone, in breast cancer." (PMID 16569247, 2006). "Moreover, synergistic or additive effects of growth inhibition between PPARγ and RXRα agonists have been found in liposarcoma and breast cancer cells." (PMID 15467764, 2004). "Additionally, independent studies showed that COX-2 and PPARγ are induced and inactivated, respectively, in human breast carcinoma." (PMID 15266333, 2004). "Furthermore, PPARγ activation influences ER signaling, particularly in breast cancer." (PMID 40926269, 2025). "Additionally, PPARG dampens the responsiveness of HER2-positive breast cancer to anti-HER2 drugs." (PMID 40303293, 2025). "After combining trastuzumab and pyrotinib to treat HER2-positive breast cancer cells, cell survival was higher in the group with excess PPARG expression, suggesting that PPARG may enhance resistance to combination therapy with dual-target drugs in HER2-positive breast cancer cells." (PMID 40303293, 2025). "Thus, PPARG is a potential therapeutic target for breast cancer treatment." (PMID 38516703, 2024). "However, PPARγ is also significantly expressed in breast cancer." (PMID 37942548, 2024). "Activation of the PPARγ/RXRα signaling pathway has been shown to inhibit cell growth, decrease tumor invasiveness, and reduce the production of pro-inflammatory cytokines in different cancer types, including colon, lung, pancreatic, prostate, and breast cancers." (PMID 37645246, 2023). "We found that activation of PPARγ transcriptional activity could oppose this transition of pericytes into myofibroblastic-like cells capable of promoting angiogenesis and the growth of breast cancer cells in vitro and in vivo." (PMID 37816052, 2023). "ER + breast cancer patient RNAseq data from TCGA revealed an association of ROS and PPAR signaling with NNAT expression and in silico analysis of the NNAT promotor revealed consensus binding sites for NRF1 and PPARα/PPARγ, as well as the cell cycle transcription factor, E2F4." (PMID 37400769, 2023). "In the case of miRNA-155, it has been suggested that EVs from breast cancer are emerging mediators of neoplastic cachexia, since they have an important role in the catabolism of adipocytes and muscle cells by targeting PPARγ (peroxisome proliferator-activated receptor gamma)." (PMID 37047783, 2023). "Hence, our data suggest that PPARγ phosphorylation might be involved in a mechanism governing immune cell repulsion in breast cancer." (PMID 36139700, 2022). "A 2020 experiment in vitro showed that PPARγ, which is commonly expressed in human primary and metastatic breast cancer, interacted with Nur77, recruited the ubiquitin E3 enzyme Trim13 to target the ubiquitin proteasomal degradation of Nur77, and promoted breast cancer progression." (PMID 36611922, 2022). "Therefore, we hypothesize that PPARγ phosphorylation may be involved in an immunosurveillance evasion mechanism employed by breast cancer cells." (PMID 36139700, 2022).
breast cancer (continued). "In addition, another study by our group described that PPARγ was expressed in almost 60% of our breast cancer panel samples with a predominant cytoplasmic location and that high cytoplasmic PPARγ expression was correlated with short OS in breast cancer patients." (PMID 35406808, 2022). "Therefore, we speculate that the histone deacetylase inhibitor Chidamide could positively feedback PPARG to act as an inhibitor of breast cancer cells." (PMID 36425653, 2022). "MCF7 breast cancer cells were treated for 24 h with NSAIDs, at the following concentrations: 0.750 mM of ibuprofen; 0.500 mM of indomethacin; 0.375 mM of diclofenac; 0.060 mM of sulindac; 0.020 mM of celecoxib; and 0.020 mM of troglitazone (as a positive control, standard agonist of PPARγ)." (PMID 35163433, 2022). "This, again, suggests that PPARγ may have anti-tumorigenic effects on cancer cells, but pro-tumorigenic effects on cells of the microenvironment, as was already described in the context of breast cancer." (PMID 35954274, 2022). "However, in 1999, researchers found that ligand-activated PPARγ could prevent the development of experimental breast cancer in vivo." (PMID 36611922, 2022). "Elevated levels of PPARγ in breast cancer tumors may be responsible for low ALOX15B expression." (PMID 36438817, 2022). "Therefore, PPARγ/HO-1 signaling pathway inhibition may be beneficial for prevention and treatment of breast cancer and its metastasis." (PMID 34199169, 2021). "Interestingly, the ratio of α : γ : δ tocopherols found in this study for ROSCO2 is close to that of α-tocopherol mix rich in γ homolog, which shows a broad anticancer activity, including reducing estrogen receptor expression and increasing PPARγ signalling in breast cancer cells." (PMID 34211628, 2021). "In the last decades, the peroxisome proliferator-activated receptor γ (PPARγ), a ligand-activated transcription factor, which has been mainly characterized as a pivotal regulator of adipocyte differentiation, has also received considerable attention for its role in breast cancer tumorigenesis." (PMID 32937951, 2020). "In addition, rosiglitazone reduces the expression of the leptin receptors, antagonizes the leptin signal, and inhibits the MAPK/STAT3/Akt pathway, suggesting that PPARγ agonists may have a potential role in the treatment of breast cancer patients." (PMID 32937951, 2020). "PLIN1 may affect tumor progression through PPARG/PPARγ pathway in breast cancer." (PMID 33029112, 2020). "Many investigations undertaken with the aim of assessing a direct effect of PPARγ agonists on different processes involved in breast carcinogenesis demonstrated that these molecules induce cell growth inhibition, trigger cell death, inhibit breast cancer cell motility, and invasion." (PMID 32937951, 2020). "Different studies have reported that activation of PPARγ by natural or synthetic ligands, such as omega (ω)-3 polyunsaturated fatty acids (PUFAs) and thiazolidinediones (TZDs), respectively, reduces breast cancer cell growth, migration and invasion in different breast cancer cell lines." (PMID 33352766, 2020). "Interestingly, it has been reported that ligand-activated PPARγ can inhibit CAF-induced effects on breast cancer cell interfering with the CXCR4/stromal cell-derived factor-1 (SDF-1) α axis, which plays a crucial role in mediating breast cancer cell invasion and metastasis." (PMID 33352766, 2020). "Finally, further investigation and additional clinical trials will confirm whether PPARγ agonists may represent a valuable tool in the prevention and treatment of breast cancer." (PMID 32937951, 2020). "Peroxisome proliferator-activated receptor γ (PPARγ), a steroid hormone receptor, was discovered by Issemann and Green in 1990 and plays an important role in the regulation of glucose and lipid metabolism in some obesity-related cancers, such as breast cancer and EC." (PMID 33197888, 2020).